PTX3 (pentraxin 3)
Diseases named in the same sentence as PTX3 in open-access papers (continued):
Sharing a sentence is not in itself a finding about the gene and the disease.
Crohn disease (4 papers, 2012 to 2024). A gastrointestinal disorder characterized by chronic inflammation involving all layers of the intestinal wall, noncaseating granulomas affecting the intestinal wall and regional lymph nodes, and transmural fibrosis. "Regarding the crucial relationship between the analyzed biomarkers and the pathogenic process during Crohn’s disease, we also assessed the usefulness of serum pro-GN, PTX3 and S100A12 measurements in evaluating disease activity." (PMID 37892129, 2023). "In our studies, we observed higher levels of PTX3 in the fibrotic phase of Crohn’s disease compared to the inflammatory stage and the control group." (PMID 39519095, 2024). "The presented work is an introduction to further assessing the usefulness of PTX3 in monitoring the development of Crohn’s disease, considering the phase and phenotype of the disease." (PMID 39519095, 2024). "Nevertheless, the higher levels of PTX3 observed in the group of patients with the stenotic form of Crohn’s disease compared to the inflammatory form in the presented study allows us to hope that it can be considered as a differentiating marker." (PMID 39519095, 2024). "The aim of our study was to evaluate the value of the PTX3 measurement as a phenotypic marker of the stenotic form of Crohn’s disease." (PMID 39519095, 2024). "In group of patients with Crohn’s disease, the implemented anti-inflammatory treatment significantly decreased the concentration of PTX3, reaching levels similar to those measured in the serum of healthy individuals." (PMID 37892129, 2023). "In this study, we aimed to evaluate the utility of pro-GN, PTX3 and S100A12 as diagnostic markers of Crohn’s disease." (PMID 37892129, 2023). "Other potential biomarkers of Crohn’s disease analyzed in this study are pentraxin 3 (PTX3) and s100A12 protein, both of whose function is related to the immune response." (PMID 37892129, 2023). "Meanwhile, the level of S100A12 also decreased, however not statistically significantly, indicating the predominance of pro-GN and PTX3 assessments in evaluating the beneficial effect of corticosteroid therapy in the course of Crohn’s disease." (PMID 37892129, 2023). "Based on the conducted research, it was suggested that the measurement of PTX3 could be used as a marker of Crohn’s disease activity." (PMID 39519095, 2024). "In this study, we also assessed the concentration of pentraxin 3 and S100A12, which are proteins related to the innate immune response and are engaged in the development of inflammation, being an integral part of the pathogenic process during Crohn’s disease." (PMID 37892129, 2023). "The conducted statistical analyses revealed a significant difference in the serum profiles of pro-GN, PTX3 and S100A12 between patients with Crohn’s disease and healthy individuals, indicating the diagnostic usefulness of all the analyzed biomarkers in this disease." (PMID 37892129, 2023). "Considering the role of the analyzed proteins in the pathogenic process and the obtained results, the measurements of serum PTX3 and S100A12 may be used during the diagnostic process for Crohn’s disease." (PMID 37892129, 2023). "Therefore, the measurements of the serum profile of PTX3 might be a helpful tool in monitoring the effect of implemented treatment in Crohn’s disease." (PMID 37892129, 2023). "Moreover, as the median CRP concentration in the blood of patients with Crohn’s disease was increased compared to the reference values, we estimated the correlation between the level of this inflammatory marker and serum profiles of pro-GN, PTX3 and S100A12." (PMID 37892129, 2023). "Consequently, PTX3 measurements in serum may reflect the intensity of the inflammatory state, being a key process in pathogenesis and development of Crohn’s disease." (PMID 37892129, 2023). "The results obtained from this investigation suggest that measurements of pro-GN, PTX3 and S100A12 could prove beneficial in the diagnosis of Crohn’s disease." (PMID 37892129, 2023).
Crohn disease (continued). "Regarding the contribution of proguanylin to intestinal barrier integrity and pentraxin 3 along with S100A12 to innate immunity, these mentioned biomarkers may be useful in the diagnosis of Crohn’s disease." (PMID 37892129, 2023). "This hypothesis is underlined by the demonstration of extracellular DNA in large bowel tissues from patients suffering from a bacterial gastrointestinal infection and Crohn's disease and by activation of NET release in response to long pentraxin 3 (PTX3)." (PMID 24381411, 2013). "Therefore, the hypothesis of our study is that pro-GN, PTX3 and S100A12 measurements in the serum of patients with Crohn’s disease are useful in diagnosing and monitoring the activity of the disease." (PMID 37892129, 2023).
cystic fibrosis (4 papers, 2012 to 2023). Autosomal recessive disorder caused by pathogenic variants in the CFTR gene (cystic fibrosis transmembrane conductance regulator), which encodes a chloride and bicarbonate channel expressed in epithelial cells, and follow the diagnosis criteria. "Recent results indicate that PTX3 has therapeutic activity in chronic lung infections by Pseudomonas aeruginosa, a major cause of morbidity and mortality in cystic fibrosis patients." (PMID 23316195, 2012). "Our observations are in concert with reported reduced levels of IL-17A upon treatment with exogenous pentraxin-3 in murine models of chronic P. aeruginosa lung infection and cystic fibrosis and suggest an inverse correlation between pentraxin-3 and IL-17A dependent pathway." (PMID 35387000, 2021).
dengue (4 papers, 2010 to 2025). "A high PTX3 concentration has also been shown to predict the severity of disease in dengue virus infection, leptospirosis and epidemic nephropathy." (PMID 23341967, 2013).
emphysema (4 papers, 2010 to 2024). "To elucidate the functional role of PTX3 in CS-induced responses, we examined pulmonary inflammation, protease/antiprotease balance, emphysema and body weight changes in WT and Ptx3 KO mice." (PMID 20920344, 2010). "We also examined the in vivo functional role of PTX3, by measuring pulmonary inflammation including lymphoid aggregate formation and emphysema in WT and Ptx3 KO mice upon CS exposure." (PMID 20920344, 2010). "However, PTX3 deficiency is not critical in CS-induced pulmonary inflammation, peribronchial lympoid neogenesis, emphysema and body weight changes in this murine model of COPD." (PMID 20920344, 2010). "CS-induced pulmonary inflammation, peribronchial lymphoid aggregates, increase in MMP-12/TIMP-1 mRNA ratio, emphysema and failure to gain weight were not significantly different in Ptx3 KO mice compared to WT mice." (PMID 20920344, 2010). "However, our results suggest that either PTX3 is not critical in CS-induced pulmonary inflammation, emphysema and body weight changes, or that its role can be fulfilled by other mediators with overlapping activities." (PMID 20920344, 2010). "However, PTX3 deficiency does not affect several pulmonary hallmarks of COPD such as inflammation, peribronchial lymphoid neogenesis and emphysema." (PMID 20920344, 2010).
endotoxemia (4 papers, 2015 to 2024). "In conclusion, using a wide array of proteomic methodologies in both human and mouse models, we elucidated a distinct relationship between PTX3 and neutrophils in the context of endotoxemia and associated vascular inflammation." (PMID 33288685, 2021). "In this study, we revealed that, compared with WT mice, Ptx3−/− mice with lipopolysaccharide (LPS)-induced endotoxemia exhibited alleviated liver damage, with reduced serum alanine transaminase and aspartate transaminase levels and an improved survival rate." (PMID 39666228, 2024). "We constructed an endotoxemia model by intraperitoneally injecting LPS (10 mg/kg) into Ptx3−/− and wild-type (WT) mice." (PMID 39666228, 2024). "Instead, neutrophil extravasation accounts for the vascular deposition of PTX3 multimers during endotoxemia." (PMID 33288685, 2021). "Second, the PTX3 response to endotoxemia consistently correlated closely to changes in cell adhesion molecules." (PMID 33288685, 2021).
esophageal cancer (4 papers, 2017 to 2025). A primary or metastatic malignant neoplasm involving the esophagus. "The authors showed that the overexpression of PTX3 in esophageal cancer cell lines reduced cell proliferation, colony formation, cell cycle, ability to migrate, as well as sensitivity to radio- and chemotherapy." (PMID 38136377, 2023). "The methylation levels of APC, ITGAV, PRDM16 and PTX3 were significantly different between esophageal cancer and healthy control tissues." (PMID 27893424, 2017). "Peripheral PTX3 is induced after protocatechuic acid treatment in esophageal cancer, which may account for the decrease in high grade dysplasia." (PMID 41479916, 2025). "In addition, it was observed to positively regulate the expression of the promoter of pentraxin 3 (PTX3), a silenced gene in esophageal cancer that inhibits angiogenesis and tumorigenesis when activated." (PMID 38611719, 2024).
hyperandrogenism (4 papers, 2020 to 2025). Excessive secretion of androgens from the adrenal glands or gonads. "The RNA-seq data indicated the upregulation of PTX3 in follicle cells from PCOS women is associated with hyperandrogenism." (PMID 33594624, 2021). "Elevated follicular PTX-3 levels are linked to hyperandrogenism and ovarian reserve in PCOS, but may impair embryo quality and functional follicular response." (PMID 41013753, 2025). "On the other hand, hyperandrogenism has been associated with low PTX3 levels." (PMID 32372340, 2020). "Overall, the circulating PTX3 level was elevated in PCOS women and significantly associated with the presence of hyperandrogenism." (PMID 34856980, 2021). "Previous study has found that PCOS women had higher PTX3 expression in follicle cells, and aberrant DNA modification and hyperandrogenism might be possible pathogenies." (PMID 34856980, 2021). "However, whether elevated circulting PTX3 is an indicator of the severity of innate immunity or is a compensatory mechanism of hyperandrogenism, and the mechanisms related androgen-induced higher PTX3 expression requires further study." (PMID 34856980, 2021). "Also, hyperandrogenism and the existence of PCOS were valuable predictors for elevated PTX3." (PMID 34856980, 2021).
IgA nephropathy (4 papers, 2016 to 2024). "PTX3 production has already been demonstrated in HPTCs, and elevated PTX3 expression levels have been documented in mesangial cells of patients with IgA nephropathy." (PMID 34064989, 2021). "The expression of PTX3 was increased in renal endothelial cells in an ischemia-reperfusion injury model and in the glomerular mesangial and endothelial cells of patients with type I membranous glomerulonephritis or IgA nephropathy." (PMID 29725602, 2018). "It has been observed that PTX3 expression increases in renal tubular epithelial cells in ischemia-reperfusion injury of the kidney, as well as in glomerular endothelial cells of patients with IgA nephropathy and type I membranous proliferative glomerulonephritis." (PMID 39697970, 2024). "Interestingly, patients with IgA nephropathy (that have been demonstrated to present with high PTX3 levels) were highly represented among those non-diabetic CKD patients that showed a SGLT2i-mediated benefit." (PMID 34064989, 2021).
inflammatory bowel disease (4 papers, 2012 to 2025). A spectrum of small and large bowel inflammatory diseases of unknown etiology. "PTX3 may therefore also be a good diagnostic marker for deterioration in patients with inflammatory bowel disease." (PMID 22347626, 2012). "In the literature review, the available studies report the involvement of PTX3 as a modulator of inflammation in inflammatory bowel disease." (PMID 39519095, 2024). "In this study, we aimed to evaluate the use of serum pro-GN, PTX3 and S100A12 measurements in the differential diagnosis of inflammatory bowel disease." (PMID 37892129, 2023).
Large vessel vasculitis (4 papers, 2016 to 2026). A type of vasculitis (inflammation of blood vessel walls) affecting large arteries such as the aorta and branches of the aorta. "Active small- or large- vessel vasculitis were the main independent variables influencing PTX3 levels at multivariate analysis." (PMID 31191526, 2019).
meningioma (4 papers, 2017 to 2024). A generally slow growing tumor attached to the dura mater. "This functional validation strengthens the association between miR-29c and PTX3 in the context of meningiomas." (PMID 38577017, 2024). "Inhibition of miR-29c-3p resulted in upregulation of PTX3, which in turn caused apoptosis of meningioma cells and decreased cell viability." (PMID 38577017, 2024). "Inhibiting miR-29c-3p has increased the expression level of PTX3 in primary meningioma cells, indicating a potential targeting of PTX3 by miR-29c." (PMID 28327132, 2017). "Inhibiting miR-29c upregulated the PTX3 level, induced apoptosis of meningioma cells, and decreased cell viability." (PMID 28327132, 2017). "miR-29c-3p and PTX3 are inversely correlated in tissues and meningioma cells, hinting that PTX3 can be regulated by miR-29c-3p." (PMID 28327132, 2017). "Markers that can play a role in meningioma pathophysiology and tumor-promoting inflammation have been determined, and the results reveal that the relationship between miR-29c-3p and PTX3 can be one of the driving forces in meningioma pathology." (PMID 28327132, 2017). "In this study, we found that miR-29c-3p is upregulated in meningiomas, whereas its predicted target PTX3 is downregulated." (PMID 28327132, 2017). "In addition, the study revealed significantly low expression of the tumor suppressor PTX3 in meningioma samples." (PMID 38577017, 2024). "Herein, we describe integrated analysis of gene networks that might play an important role in the initiation and progression of meningiomas, with emphasis on the downregulation of tumor suppressor PTX3 via miR-29c." (PMID 28327132, 2017). "The oncosupressor PTX3 was constitutively low in meningioma samples." (PMID 28327132, 2017). "Our data show that the tumor suppressor PTX3 is constitutively downregulated in meningiomas." (PMID 28327132, 2017). "PTX3 level was negatively correlated with tumor volume and progesterone receptor level in our cohort which supports the argument that the gene can act as a tumor suppressor for meningioma." (PMID 28327132, 2017). "The PTX3 gene expression level increased significantly in primary cell lines MEN-117 and MEN-141, suggesting a regulation of the gene by miR-29c-3p in meningiomas." (PMID 28327132, 2017).
neutropenia (4 papers, 2021 to 2025). A decrease in the number of neutrophils found in the blood. "An independent predictor for invasive infections was represented by homozygosity for the minor allele of PTX3 rs2305619 and/or rs3816527 in patients with neutropenia." (PMID 36499628, 2022). "Thus, we cannot conclude that PTX3 is a biomarker of high risk of mortality in patients with chemotherapy‐induced neutropenia, although it remains a strong marker of severe infections." (PMID 40722110, 2025). "Since PTX3 is released earlier than CRP during inflammation, PTX3 is an attractive biomarker for patients with neutropenia that require prompt and appropriate care." (PMID 40722110, 2025). "Due to the longer duration of neutropenia after double induction, PTX3 might play a more important role in the occurrence of IFD in the validation cohort compared to the stratification cohort." (PMID 38982248, 2024). "In summary, our study shows a statistically significant association between SNPs of the PTX3 (rs2305619/rs1840680, rs3816527) and Dectin-1 (Y238X, rs16910526) genes and the development of IFD intensive induction chemotherapy induced neutropenia in AML patients." (PMID 38982248, 2024). "Neutrophils are responsible for both production and storage of PTX-3 and neutropenia could lead consequently to impaired immune mechanisms as PTX-3 ability to opsonize microbial surfaces would be hampered." (PMID 36499628, 2022). "Another study reports on the significant interaction of the PTX3 rs2305619 and rs3816527 SNPs in AML patients and pre-existing neutropenia when developing IFD." (PMID 38982248, 2024).
Parkinson disease (4 papers, 2016 to 2024). A progressive degenerative disorder of the central nervous system characterized by loss of dopamine producing neurons in the substantia nigra and the presence of Lewy bodies in the substantia nigra and locus coeruleus. "Most importantly, increased Ptx3 secretion may correlate with neurodegenerative disease progression, such as Alzheimer’s disease and Parkinson’s disease." (PMID 36633805, 2023). "In addition, serum levels of PTX3 have been proposed as a novel biochemical marker in Parkinson’s disease." (PMID 36012705, 2022). "Pentraxin-3 (PTX3) is an inflammatory marker and its plasma levels are increased in patients with Parkinson's disease." (PMID 27344170, 2016).
Pleural effusion (4 papers, 2014 to 2024). The presence of an excessive amount of fluid in the pleural cavity. "Recently, two further biomarkers have been evaluated in the early diagnosis of pleural effusions: pentraxin-3 (PTX-3) and procalcitonin (PCT)." (PMID 34179342, 2021). "We planned a comparative analysis to assess the predictive accuracy and diagnostic significance of PCT and PTX-3 compared to established biochemical markers (CRP and ADA) in the early differential diagnosis of pleural effusions." (PMID 34179342, 2021). "Serum and pleural fluid PCT and PTX-3 levels might be useful early biomarkers to diagnose pleural effusions’ etiology." (PMID 34179342, 2021). "Evaluation of serum and pleural fluid PCT and levels of PTX-3 in the pleural fluid may be used as an early biomarker to differentiate the etiology of pleural effusion." (PMID 34179342, 2021). "We evaluated two established (ADA, CRP) and two more recent biomarkers (PTX-3 and PCT) in serum and pleural fluid separately to find their accuracy and efficiency to discriminate pleural effusion." (PMID 34179342, 2021). "The primary aim of the study was to assess the predictive accuracy of procalcitonin (PCT) and pentraxin-3 (PTX-3) in comparison to other biochemical markers such as C-reactive protein (CRP), and adenosine deaminase (ADA) in the differential diagnosis of pleural effusions." (PMID 34179342, 2021). "High concentrations of Pentraxin-3(PTX-3) in pleural effusions are very sensitive to differentiate PPE from non-PPE, while they do not seem able to differentiate between uncomplicated and complicated pleural effusions." (PMID 25243068, 2014).
pulmonary hypertension (4 papers, 2012 to 2022). Increased pressure within the pulmonary circulation due to lung or heart disorder. "Our findings suggest that PTX3 does not reflect the cardiac burden due to the pulmonary hypertension, but rather the activity of pulmonary vascular degeneration because PTX3 levels were significantly decreased after active treatment specifically for PAH." (PMID 23029266, 2012).
pulmonary tuberculosis (4 papers, 2010 to 2023). A bacterial infection that affects the lungs and is caused by Mycobacterium tuberculosis. "In addition, PTX3 plasma levels were significantly higher in Egyptian patients with pulmonary tuberculosis than healthy individuals." (PMID 38053036, 2023).